TCF4 (transcription factor 4)
Diseases named in the same sentence as TCF4 in open-access papers (continued):
Sharing a sentence is not in itself a finding about the gene and the disease.
tumor (continued). "Altogether these data show that β-catenin/TCF4 bind Wnt-responsive element (WRE)-encompassing enhancers specifically active in PRNP in human β-catenin activated tumor cells." (PMID 38589873, 2024). "Then, we investigated the single nucleotide variant (SNV) frequency of TCF4, TCF3, and TCF7 in each tumor based on TCGA data." (PMID 39205642, 2024). "Li found that MDSCs in contact with tumor cells can enhance the expression of Cyclooxygenase-2 (COX-2) in tumor cells, activate the β-catenin/TCF4 pathway, and promote the occurrence of EMT in tumor cells." (PMID 37857728, 2023). "Bioinformatics data analysis and experimental data showed that TCF4 promoted tumor development by inhibiting endoplasmic reticulum stress." (PMID 37337284, 2023). "We found thatLEF1 and TCF3 are over-expressed in breasttumors regarding non-tumor samples, while TCF4 andTCF7 are down-expressed, with the gene’s methylation statusbeing associated with its expression dysregulation." (PMID 38100720, 2023). "Tumor growth was reduced as well as β-catenin, transcription factor 4 (TCF4), protein kinase B (AKT), signal transducers and activators of transcription 3 (STAT3), and proliferating-cell nuclear antigen (PCNA) expression." (PMID 36986798, 2023). "Multi-tissue tumor studies have shown that TCF4 is highly expressed in human malignancies with aberrant Wnt/β-catenin signaling, and that aberrant intracellular β-catenin accumulation and nuclear translocation can also enhance TCF4 transactivation." (PMID 37337284, 2023). "FAKi prevents nuclear relocation of the complex and allows, in the context of VM formation during tumor development, to enhance TCF-4 activity by boosting the expression of TCF-4-dependent genes." (PMID 36797281, 2023). "Significant upregulation of expression is found in genes associated with tumor cell invasion such TGFβ1, ROAR, DAB2, BMP6, NOS2, PLXN2, and CADPS, whereas TCF4 was significantly downregulated in AHCY deficient cells." (PMID 38003292, 2023). "RUNX3 had the ability to form a ternary complex with beta-catenin/TCF4, leading to the suppression of Wnt signaling activity and the suppression of tumor." (PMID 38007527, 2023). "Two weeks after modeling, the tumor volume of subcutaneous xenografts increased, and the xenograft tumors in the TCF4 group grew faster than those in the Mock group." (PMID 37337284, 2023). "Aberrant activation of TCF4 further enhances its binding to target gene E-box sequences, activating target genes transcription and promoting tumor proliferation, vascular invasion, and distal metastasis." (PMID 37337284, 2023). "At the same time, FOXP3 can co-activate the formation and function of β-catenin and the TCF4 (transcription factor 4) complex in the nuclei of tumor cells." (PMID 36235242, 2022). "The inhibition of the β-catenin-TCF4-CEGRs/ALCDs axis inhibits the proliferation of cancer cells and tumor growth in HBL cell lines and HBL-PDXs." (PMID 36551548, 2022). "As a practical TNIK inhibitor, NCB-0846 can bind to the ATP active pocket of TNIK, making it unable to phosphorylate TCF4, thereby exerting a tumor suppressive effect." (PMID 36287174, 2022). "In non-small cell lung cancer cells, nutlin-3 treatment was able to reduce TCF4 expression and thereby sensitize tumor cells to axitinib-induced apoptosis." (PMID 35327645, 2022).
tumor (continued). "Previously, TCF4 presented elevation in the GC cells, higher levels of TCF4 indicated poorer prognosis of GC, and miR-133a-5p functioned as a GC tumor suppressor through targeting TCF4." (PMID 36204179, 2022). "Further analyses in the TCGA and GEO database revealed that TCF4 expression was significantly upregulated in tumor tissues compared with that in normal tissue counterparts and both TCGA and histological subtypes." (PMID 35534546, 2022). "We found that TCF4 knockout suppressed tumor growth and enhanced sensitivity to cisplatin; however, it did not influence mice weight." (PMID 35534546, 2022). "PNU-74654 blocks the interaction between β-catenin and TCF4, thereby preventing the transcription of tumor-related proteins in the affected testis or in metastatic lesions." (PMID 35723395, 2022). "Mechanistically, this occurs as a result of the β-catenin/TCF4 complex binding to the PD-L1 promoter, leading to increased transcription, so that APC mutations can induce tumor immune evasion via an immune checkpoint pathway." (PMID 35937946, 2022). "A study showed that DAXX silencing in OSCC cells suppresses cyclin D1 expression via the DAXX-TCF4 (transcription factor 4) interaction, thereby reducing tumor growth." (PMID 35087762, 2021). "Meanwhile, HE staining and quantification of tumor area indicated that TCF4 silencing limits hepatic metastases in the orthotopic model." (PMID 34580284, 2021). "In conclusion, circ_0001721 increased DXR resistance and promoted tumor progression in OS via regulating miR-758/TCF4 axis through Wnt/β-catenin pathway." (PMID 34215252, 2021). "TCF4 expression was significantly increased in tumour area compared with non‐tumour, which suggesting TCF4 promotes hepatocytes proliferation in the human liver." (PMID 33951279, 2021). "TCF4 and its target gene c-Myc are important nodes in Wnt-β-catenin signaling, which is an essential pathway affecting cell stemness and tumor progression." (PMID 33648560, 2021). "Some strategies and drugs have been proposed to target this pathway, such as blocking receptors/ligands, targeting intracellular molecules, beta-catenin/TCF4 complex and its downstream target genes, or tumor microenvironment and immune response." (PMID 34488905, 2021). "mRNA expression using qRT-PCR showed approximately 83% decreased TCF-4 mRNA expression in tumor tissue and adjoining mucosa compared to normal mucosa." (PMID 32265994, 2020). "Cyclin D1 and c-Myc are common downstream molecules of the β-catenin/TCF4 complex and are related to cell proliferation, migration and invasion in a variety of tumor mechanisms 68-70." (PMID 32373221, 2020). "APC mutation promotes CRC initiation through the activation of β-catenin and transcription-factor-4 (TCF4) complex which targets tumor progression-promoting genes, such as Myc, cyclin D1, and matrix metallopeptidase 7 (MMP7)." (PMID 33271948, 2020). "Out of 60 tumor cases, all were positive for TCF-4 protein expression and 5 cases had a mutation in the TCF-4 gene." (PMID 32265994, 2020). "We selected LRP1B and TCF4 (ITF2) genes that were completely deleted in the same tumor type or at least three of the four cell lines, respectively." (PMID 32224864, 2020). "Statistically significant variation was observed in the staining of TCF-4 protein in case of tumor (p < 0.001), adjoining (p < 0.001) and normal mucosa (p < 0.001) between the nuclear and cytoplasmic stain." (PMID 32265994, 2020). "In mice, the epithelial expression of TCF4 is indispensable for cell proliferation and tumor initiation but in humans, the TCF4 role is redundant with the related TCF1 and LEF1 transcription factors." (PMID 32053894, 2020).
tumor (continued). "This seems to provide one explanation for the surprising observations that TCF4 functions as a tumour suppressor in colon tumourigenesis." (PMID 32961708, 2020). "Confocal microscopy and western blot analysis also confirmed the results of immunohistochemistry, indicating reduced expression of TCF-4 protein in tumor tissues as compared to normal and adjoining mucosa of CRC patients." (PMID 32265994, 2020). "The abnormal Wnt/β-catenin signaling pathway activation with increased TCF4 and LEF1 levels is also implicated in tumorigenesis and tumor progression in various cancer types." (PMID 32933177, 2020). "The TCF-4 expression in normal tissues was high as compared to that in tumor tissues as well as in adjoining mucosa." (PMID 32265994, 2020). "Overall, weak expression of TCF-4 protein was observed in tumor tissues as compared to normal or adjoining mucosa." (PMID 32265994, 2020). "The observed downregulation of TCF-4 protein in tumor tissues further confirmed the results of immunohistochemistry." (PMID 32265994, 2020). "TCF-4 protein was expressed in all the tumor tissues and in all the adjoining and normal mucosa samples examined." (PMID 32265994, 2020). "Densitometric analysis showed a significant decrease in the TCF-4 protein expression in tumor and adjoining tissues compared to normal tissues." (PMID 32265994, 2020). "TCF-4 protein was expressed in 100% (20/20) of the tumor tissues analyzed with cytoplasmic positivity in 10% (2/20) of cases, nuclear expression in 25% (5/20) of cases, and 65% (13/20) of cases showed both nuclear and cytoplasmic positivity." (PMID 32265994, 2020). "Altogether, these data indicate that FOXO1 induces GSK3β to reduce β-catenin/TCF4-mediated tumor stemness and EMT signals." (PMID 31754475, 2019). "The results above indicated that the DNMT3B-induced downregulation of HOXB13 mediates methylation and regulates C-myc expression via β-catenin/TCF4 signaling, enhancing tumor progression and resulting in a poor prognosis." (PMID 31815008, 2019). "miR-15b, a bona fide tumor-suppressor miRNA, regulates a number of genes associated with CRC metastases such as AKT3, PIK3R18, GPC633, LIMS134, and TCF4." (PMID 31676795, 2019). "In the HCT-116 and HT-29 cell lines, miR-139-5p suppress CSCs self-renewal, tumorsphere formation, tumor metastasis, and recurrence as well as stem maker expression via inhibition of transcription factor 4 (TCF4, also known as E2-2)." (PMID 31861404, 2019). "Numerous studies have established the pivotal roles of β-catenin and TCF-4 as essential oncogenes of tumorigenesis, differentiation, and proliferation of tumor cells in the Wnt signaling pathway." (PMID 30867651, 2019). "Consistently, inhibition of tumor growth by ESRRG overexpression in a xenograft mouse model was rescued by the re-introduction of TCF4/LEF1, and Ki67 expression was also rescued." (PMID 29765046, 2018). "The secretion of IL-1β by macrophages is also required to activate Wnt signaling and β-catenin/TCF4 transcriptional activity in tumor cells promoting tumor growth." (PMID 30619282, 2018). "In summary, our results showed the importance of the Tcf4 Wnt effector, mainly in the mouse model of adult intestinal epithelium homeostasis and tumor initiation." (PMID 30200414, 2018). "Further DY131 treatment of xenograft tumor samples led to decreased expression of Ki67, the three Wnt components (TCF4, LEF1, and β-catenin), and the CCND1 Wnt downstream target gene." (PMID 29765046, 2018). "We showed that in adult mice, epithelial expression of Tcf4 is indispensable for cell proliferation and tumor initiation." (PMID 30200414, 2018). "The decreased expression of hsa-miR-139 can induce tumor progression via the β-catenin/TCF-4 signaling pathway." (PMID 29907753, 2018). "In this study, we found that GLUT3 is a direct target gene of TCF4/β‐catenin in tumor cells from HB." (PMID 28923827, 2017).
tumor (continued). "Two critical downstream effectors of the Wnt/β-catenin signaling pathway, TCF4 and its coactivator β-catenin, are considered to be potent oncogenes in tumor progression." (PMID 28337453, 2017). "In xenograft model, TCF-4 silence-improved tumor lesions in lungs and survival time of LLC-tumor bearing mice were abolished by MMP-15 overexpression." (PMID 27046058, 2016). "TCF4 and coactivator β-catenin are two key downstream effectors of the wnt/β-catenin signaling pathway, and considered as potent oncogenes in tumor progression." (PMID 27846906, 2016). "Significant loss of RXRα was evident in tumors as well as in tumor-free areas of intestine after 56Fe radiation and this could contribute to decreased proteasomal targeting of β-catenin, therefore enhancing cell survival and proliferation through β-catenin/TCF4 signaling." (PMID 26500891, 2015). "AMA-treated tumor spheroids demonstrated suppressed expression levels of β-catenin and its signaling components including TCF-4, NF-κB, and cyclin D1, which provides a partial explanation of how AMA was able to inhibit tumor spheroid formation." (PMID 23840269, 2013). "Using tumor cells other than CaP, we also showed that regulation of TCF4-mediated BCL2 by BMI1 is universal." (PMID 23671559, 2013). "Ser552 phosphorylation results in β-catenin translocation from the cytosol into the nucleus, increasing Tcf4/Lef1 transcriptional activity and promoting tumor cell invasion." (PMID 20858269, 2010). "In sum, the phosphorylation of β-catenin at Ser552 by AKT1 increases nuclear translocation and retention, enhancing Tcf4/Lef1 complex transcriptional activity to promote tumor cell invasion and stem cell migration." (PMID 20858269, 2010). "A representative specimen demonstrated that p-c-Jun and TCF4 were colocalized predominantly in the nuclei in a majority of the tumor cells." (PMID 18992165, 2008). "Conversely, increased nuclear β-catenin/TCF4 activity imposes a crypt progenitor phenotype on tumor cells." (PMID 17615082, 2007). "The tumor tissues were subsequently analyzed by WB for TCF4 protein expression." (PMID 39119816, 2025). "For instance, METTL3 is essential for the development and maintenance of myeloid leukemia in both mice and humans, modulates the Wnt/β-catenin-EMT axis in ESCC by stabilizing β-catenin/TCF4 transcriptional complexes to facilitate tumor invasion, and facilitates TGFβ signals to support tumor growth." (PMID 40612868, 2025). "Finally, in another study, we showed that Tcf4 is essential for both proliferation and tumor formation in the small and large intestines of mice." (PMID 40221753, 2025). "Tumor cells enhance the phosphorylation of VE-Cadherin at the Y658 residue, which promotes the formation of a VE-Cadherin/β-catenin complex and increases the transcriptional activity of TCF-4." (PMID 41019994, 2025). "Recent studies have shown that overexpressed DSTN can upregulate the activity of Wnt/β-catenin signaling pathway by promoting the nuclear translocation of β-catenin and the interaction between β-catenin and TCF4, thereby promoting tumor proliferation and metastasis." (PMID 38649690, 2024). "Gene expression analyses across these cell clusters confirmed that Ascl1/GFP, along with ASCL1 canonical NOTCH signaling target genes (Dll3, Notch1, Hes5) and the bHLH E-protein co-binding partners (Tcf4, Tcf12) were significantly elevated in Ascl1-OE tumor cells compared to control." (PMID 39609428, 2024). "Interestingly, some findings were conflicting for TCF4, especially a potential tumour suppressive role of the gene in intestinal cancer cells or tumours." (PMID 36766788, 2023).
tumor (continued). "Combined with the high correlation between the tumor suppression of oridonin and endoplasmic reticulum stress, it is essential to investigate whether the ER stress regulation of TCF4 is connected to the tumor-suppressive effects of oridonin." (PMID 37337284, 2023). "Notably, SPIN1 acts as a transcriptional coactivator of ß-catenin and T cell Factor 4 (TCF-4) enhancing their contribution to Wnt/TCF-4 pathways, which leads to tumor progression." (PMID 37055532, 2023). "QRT-PCR showed that tumor sections of HBL patients also often have increased TCF4." (PMID 36551548, 2022). "Circ-TCF4.85 knockdown in HCC exhibited the ability to reverse the tumor-suppressive effects." (PMID 36672755, 2022). "Additionally, TCF4 inhibition or knockout significantly enhanced tumor sensitivity to cisplatin in vitro and in vivo by triggering ferroptosis." (PMID 35534546, 2022). "stated overexpression of TSLC1 downregulated the transcriptional activity of TCF4/β-catenin and inhibited the mRNA or protein expression of Wnt target genes cyclinD1 and c-myc, which could suppress tumor cell migration, invasion, apoptosis." (PMID 36523593, 2022). "Therefore, a small molecule that can block the interaction between β-catenin and TCF4 can prevent the transcription of a variety of tumor-related proteins, such as c-myc, cyclin D1, Bcl-w, MDR1, IL-8 and ZEB1." (PMID 35723395, 2022). "The results showed that the protein expression levels of β-catenin, TCF4 and cyclin D1 in the tumor-adjacent tissues were significantly lower than those in the normal tissues, suggesting that ALV-J inhibited cell growth and development by decreasing the Wnt/β-catenin signaling pathway." (PMID 36461084, 2022). "Given the functions of TCF4 and MALAT1 as tumor suppressors, targeting the functional elevation of TCF4 and MALAT1 could be therapeutically beneficial against tumorigenesis." (PMID 36084949, 2022). "Moreover, we demonstrated that tumor cell-derived CCL2 was controlled by TCF4 through binding to the promoter region." (PMID 34580284, 2021). "Moreover, overexpression of TCF4 reduced the apoptosis rate of tumor tissues after radiotherapy in the presence of si-ENC1." (PMID 34362881, 2021). "One tumor harboring a novel fusion (TCF4:PLAG) was finally recorded as unclassified." (PMID 33803647, 2021). "TCF4 or CCL2 silencing in the tumor cells prevent CRC liver metastasis in the mouse model." (PMID 34580284, 2021). "It suggested that CAFs and EMT-related genes, the high expressions of FN1, ZEB1 and TCF4 in the tumor microenvironment may be involved in TCM syndromes classification in CRC." (PMID 34876190, 2021). "Also, we found that overexpression of TCF4 significantly promoted the resistance of RaR cells to radiotherapy in vivo and enhanced tumor growth rate." (PMID 34362881, 2021). "In the current study, mutational analysis of the TCF-4 gene for exon 1 revealed the presence of point mutations in 5 tumor samples, with a frequency of 8.33%, whereas no mutations were observed in adjoining and normal mucosa of exon 1 of the TCF-4 gene." (PMID 32265994, 2020). "Similarly to mRNA expression analysis, the results of the western blot analysis also showed a decrease in the expression of TCF-4 protein both in tumor and adjoining tissues (~ 55%) compared to normal tissues." (PMID 32265994, 2020). "The observed downregulation of TCF-4 expression at the protein level in tumor specimens revealed that TCF-4 may act as a tumor suppressor in these subjects." (PMID 32265994, 2020). "LEF1 activates β-catenin/TCF4 transcriptional activity, promoting tumor growth and progression." (PMID 32933177, 2020). "Since SEs often recruit a high density of transcription factors and coactivators to drive oncogene expression in tumor cells 9, 30, 31, we hypothesized that TCF4 might be responsible for maintaining AJUBA-SE activity." (PMID 32802179, 2020). "Core-derived tumor tissues rather displayed high levels of TCF4." (PMID 31410187, 2019).